ADGRA3 (adhesion G protein-coupled receptor A3)
Description:
Orphan receptor that may have a role in planar cell polarity pathway.
Synonyms: GPR125; FLJ38547; PGR21; TEM5L
Tractability: Antibody: UniProt predicts a signal peptide or a membrane-spanning region; its Gene Ontology location is reachable by antibodies, with medium confidence. PROTAC: ubiquitination databases record sites on it; its protein half-life has been measured.
Target class: Family B G protein-coupled receptor; Membrane receptor
Gene: Protein-coding gene on chromosome 4 (22,345,071 to 22,516,089, reverse strand). Ensembl gene ENSG00000152990.
Subcellular location: Membrane
Gene Ontology:
Molecular function: protein binding; G protein-coupled receptor activity; transmembrane signaling receptor activity
Biological process: cell surface receptor signaling pathway; G protein-coupled receptor signaling pathway
Cellular component: external side of plasma membrane; membrane; plasma membrane
Genetic constraint (gnomAD): Loss-of-function variants: 50 observed, 104.28 expected, observed/expected ratio (o/e) 0.48, 90% interval 0.38 to 0.61. The upper end of that interval is the gene's LOEUF score, 0.61, which puts it in group 2 of 6, group 1 being the genes least tolerant of losing a copy. Missense variants: 1,371 observed, 1,503.8 expected, observed/expected ratio (o/e) 0.91, 90% interval 0.87 to 0.95. Synonymous variants: 529 observed, 556 expected, observed/expected ratio (o/e) 0.95, 90% interval 0.88 to 1.02.
Homologues: Orthologues: chimpanzee ADGRA3 (99% identical), macaque ADGRA3 (99% identical), pig ADGRA3 (95% identical), mouse Adgra3 (93% identical), rat Adgra3 (91% identical), guinea pig ADGRA3 (90% identical), dog ADGRA3 (89% identical), tropical clawed frog adgra3 (79% identical), zebrafish adgra3 (33% identical). Paralogues in human: ADGRA2 (43% identical), ADGRA1 (18% identical), ADGRL1 (14% identical), ADGRL2 (14% identical), ADGRB3 (14% identical), ADGRB1 (14% identical), ADGRB2 (13% identical), ADGRL3 (13% identical), ADGRG4 (12% identical), ADGRG6 (12% identical), ADGRF5 (11% identical), ADGRE5 (11% identical), and 30 more.
Diseases named in the same sentence as ADGRA3 in open-access papers:
ADGRA3 is named in the same sentence as 22 diseases in open-access papers, as found by Europe PMC text mining. Sharing a sentence is not in itself a finding about the gene and the disease. The quoted sentences say what the papers report.
Azoospermia (2 papers, 2024 to 2025). Absence of any measurable level of sperm,whereby spermatozoa cannot be observed even after centrifugation of the semen pellet. "In previous reports, male mice deficient in ADGRA3 showed obstructive azoospermia with high penetrance." (PMID 39718208, 2024). "ADGRA3 was initially identified as a spermatogonial stem cell marker, and the knockdown of ADGRA3 in male mice leads to obstructive azoospermia with high penetrance, while female mice lacking ADGRA3 develop a closed vagina to a similar extent." (PMID 40127866, 2025).
autosomal recessive retinitis pigmentosa (1 paper, 2022). Autosomal recessive retinitis pigmentosa (RP) is an autosomally recessive inherited retinal dystrophy leading to progressive loss of the photoreceptors and retinal pigment epithelium and resulting in blindness usually after several decades. "A novel splicing variant in ADGRA3 was identified in a heterozygous state, while ADGRA3 is known to cause autosomal recessive retinitis pigmentosa, and thus can not be disease-causing in this state." (PMID 35033039, 2022).
Bardet–Biedl syndrome 19 (1 paper, 2024). "While pathogenic variants in USH1C and IFT27 are associated with autosomal recessive Usher syndrome type 1C and Bardet–Biedl syndrome 19, respectively, mutated ADGRA3 is linked to autosomal recessive RP." (PMID 39766861, 2024).
breast carcinoma (1 paper, 2022). "We further investigated GPR125/ADGRA3 expression in human breast cancer patients within the METABRIC and the TCGA datasets downloaded from the cBioPortal platform." (PMID 35302059, 2022). "The highest expression of ADGRA3 was found within basal-type breast cancers within in the PAM50 classification of both databases and in microarray analyses." (PMID 35302059, 2022).
Hepatic steatosis (1 paper, 2024). Steatosis is a term used to denote lipid accumulation within hepatocytes. "Meanwhile, hematoxylin-eosin staining showed that Adgra3 knockdown induced adipose expansion in iWAT, eWAT, and BAT but not lead to hepatic steatosis." (PMID 39718208, 2024).
infertile (1 paper, 2024). "We generated a global Adgra3−/− mouse line and observed imperforate vagina in 44% of Adgra3−/− females, resulting in distension of the reproductive tract and infertility." (PMID 38589878, 2024). "We, therefore, disrupted endogenous Adgra3 and found that 44% of ADGRA3-deficient females are infertile due to a lack of vaginal canalization at sexual maturity." (PMID 38589878, 2024).
Insulin resistance (1 paper, 2024). Increased resistance towards insulin, that is, diminished effectiveness of insulin in reducing blood glucose levels. "Taken together, hesperetin activates the adipose thermogenic program and improves the metabolic homeostasis in diet-induced obese mice against obesity and insulin resistance in vivo, which is ADGRA3 dependent." (PMID 39718208, 2024). "The insulin tolerance test (ITT) showed that Adgra3 overexpression alleviated the insulin resistance of HFD mice." (PMID 39718208, 2024). "Taken together, Adgra3 overexpression activates the adipose thermogenic program and improves the metabolic homeostasis in diet-induced obese mice against obesity and insulin resistance in vivo." (PMID 39718208, 2024). "Moreover, hesperetin was identified as a potential agonist of ADGRA3, capable of inducing adipocyte browning and ameliorating insulin resistance in mice." (PMID 39718208, 2024).
male infertility (1 paper, 2024). The inability of the male to effect fertilization of an ovum after a specified period of unprotected intercourse. "ADGRA3 was initially described as a marker for spermatogonial stem cells, and we recently identified it as a factor of male infertility due to ejaculatory duct obstruction in half of all male mice lacking ADGRA3." (PMID 38589878, 2024).
Obesity (1 paper, 2024). Accumulation of substantial excess body fat. "Nevertheless, our findings underlie a potential therapeutic feature of ADGRA3 and hesperetin in obesity and the associated metabolic diseases from the thermogenic viewpoint of beige fat." (PMID 39718208, 2024). "Hesperetin activated the adipose thermogenic program and facilitated metabolic homeostasis in mice with diet-induced obesity (DIO) dependent on ADGRA3." (PMID 39718208, 2024). "Adgra3 overexpression activated the adipose thermogenic program and facilitated metabolic homeostasis in mice with diet-induced obesity (DIO)." (PMID 39718208, 2024). "Nevertheless, the precise role of ADGRA3 in the progression of obesity and adipose thermogenesis remains uncertain." (PMID 39718208, 2024). "Therefore, our research subsequently shifted towards investigating the potential regulatory role of ADGRA3 in obesity and brown fat." (PMID 39718208, 2024). "This suggests that targeting the ADGRA3-Gs-PKA-CREB signaling pathway could potentially be a therapeutic approach for obesity and related metabolic disorders." (PMID 39718208, 2024). "Consequently, our study has confirmed that the knockdown of Adgra3 exacerbates obesity and disrupts glucose homeostasis." (PMID 39718208, 2024).
cancer (6 papers, 2008 to 2025). A tumor composed of atypical neoplastic, often pleomorphic cells that invade other tissues. "Furthermore, ADGRA3 expression is associated with various cancers showing both oncogenic and tumor-suppressive effects." (PMID 40127866, 2025). "Since then, it has been shown that ADGRA3 is expressed in both mammary progenitors, lacrimal gland progenitors, in male and female reproductive tract development, in osteoclastogenesis, in the brain with upregulation after brain injury, as well as playing a role in several cancers." (PMID 40127866, 2025). "ADGRA3 (GPR125) is an orphan adhesion G protein–coupled receptor (aGPCR) involved in planar cell polarity, primarily through recruitment of the signaling components disheveled (DVL) during vertebrate gastrulation and discs large homolog 1, implicated in cancer." (PMID 40127866, 2025). "ADGRA3 was significantly higher in the METABRIC integrative cluster 10, defined as a basal-like cancer enriched subgroup with high genomic instability and alteration of key cell-cycle-related genes." (PMID 35302059, 2022).
tumor (5 papers, 2008 to 2025). "In mammary progenitors, ADGRA3 expression congregates at ductal tips during morphogenesis, and high expression predicts early tumor onset and poor outcome." (PMID 40127866, 2025).
ADGRA3 also shares sentences with these, for which no sentence is quoted: depression (2 papers); osteoporosis (2); Rb (2); cerebral cancer (1); colorectal cancer (1); injury (1); metabolic disease (1); Retinal dystrophy (1); Spinocerebellar ataxia (1); teratoma (1); triple-negative breast carcinoma (1).